KRT4 (keratin 4)
Diseases named in the same sentence as KRT4 in open-access papers:
KRT4 is named in the same sentence as 67 diseases in open-access papers, as found by Europe PMC text mining. Sharing a sentence is not in itself a finding about the gene and the disease. The quoted sentences say what the papers report.
White sponge nevus (7 papers, 2011 to 2024). Any hereditary mucosal leukokeratosis in which the cause of the disease is a mutation in the KRT4 gene. "Mutation of the KRT4 gene leads to the development of white sponge nevus, which is characterized by oral leukoplakia." (PMID 28977904, 2017). "White Sponge Nevus (WSN) is traditionally considered a benign genetic disorder affecting the oral mucosa, primarily caused by pathogenic mutations in keratin 4 (KRT4) or keratin 13 (KRT13)." (PMID 38773401, 2024). "White sponge nevus (WSN) is a rare autosomal dominant disease with a family history, often caused by mutations of the keratin 4 (K4) and keratin 13 (K13) genes in patients." (PMID 36553451, 2022). "As shown in the results of previous studies, the genetic effect of KRT4 and KRT13 mutations, a member of the keratin family, is mainly implicated in the pathogenesis of white sponge nevus (WSN) disorder, a rare autosomal dominant disorder in oral mucosa." (PMID 35456240, 2022).
prostate carcinoma (5 papers, 2017 to 2025). A carcinoma that arises from epithelial cells of the prostate gland. "Genes C1orf114, CA3 and KRT4 were reported to be associated with prostate cancer, hepatocellular carcinoma and esophageal squamous cell carcinoma, respectively." (PMID 31640538, 2019). "Age-associated increased KRT4 mRNA has been linked to prostate cancer; however, its role in sperm function is unknown." (PMID 40649876, 2025).
squamous cell carcinoma (5 papers, 2006 to 2025). A carcinoma arising from squamous epithelial cells. "KRT4, for example, is highly expressed in the squamous cell carcinoma subtype of urothelial carcinoma, which is linked to poor prognosis." (PMID 40004083, 2025). "In the development of oral squamous cell carcinoma and squamous cell carcinoma of mobile tongues, a decrease in the expression of KRT4 and KRT13 has been shown." (PMID 38540309, 2024). "Therefore, the co-down-regulation of CRNN and KRT4 might synergistically promote the progression of squamous cell carcinomas like HNSCC." (PMID 39596132, 2024).
cervical cancer (4 papers, 2016 to 2025). A primary or metastatic malignant neoplasm involving the cervix. "On the other hand, LUM, BGN and KRT4 significantly decreased in cervical cancer samples." (PMID 27690342, 2016). "Western blot analysis confirmed that LYZ, ORM1, LYN, STMN1 significantly increased in cervical cancer, while LUM, BGN, KRT4 significantly decreased." (PMID 27690342, 2016).
Oral leukoplakia (4 papers, 2017 to 2023). A thickened white patch on the oral mucosa that cannot be rubbed off. "KRT4 expression is downregulated in leukoplakia and oral squamous cancer carcinomas." (PMID 35328735, 2022).
oral squamous cell carcinoma (4 papers, 2022 to 2024). "KRT4 inhibits the development of oral squamous cell carcinoma and the expression of KRT4 is downregulated due to m6A methylation at the exon-intron boundary preventing intron splicing of KRT4 pre-mRNA in oral squamous cell carcinoma." (PMID 38302910, 2024).
pterygium (4 papers, 2009 to 2022). A wedge-shaped fibrovascular lesion arising from the bulbar conjunctiva and extending to the cornea. "The most abundant complementary DNAs from pterygium include clusterin, keratins 13 (Krt13) and 4 (Krt4), S100A9/calgranulin B, and spermidine/spermine N1-acetyltransferase (SAT1)." (PMID 19956562, 2009).
breast carcinoma (3 papers, 2019 to 2024). "Moreover, when estrogen receptor β (ERβ) was silenced in breast cancer MDA-MB-231 cells, KRT4 expression was significantly increased." (PMID 34062972, 2021).
esophageal squamous cell carcinoma (3 papers, 2015 to 2019). Esophageal squamous cell carcinoma (ESCC) is a type of esophageal carcinoma (EC) that can affect any part of the esophagus, but is usually located in the upper or middle third. "KRT4, which encodes CK4 protein, was also unregulated in cluster B, and is known to be down-regulated in OSCC and esophageal squamous cell carcinoma compared to normal squamous epithelium." (PMID 28977904, 2017). "KRT4, the keratin most evolutionarily similar to KRT78 in humans, is highly expressed in the esophagus and downregulated in esophageal squamous cell carcinoma." (PMID 26039063, 2015). "In an effort to gain insight into the potential function of KRT78, we performed phylogenetic analysis of all type II epithelial keratins and identified KRT78 as most closely related to keratin 4 (KRT4), which is downregulated in esophageal squamous cell carcinoma." (PMID 26039063, 2015).
ovarian carcinoma (3 papers, 2014 to 2022). A malignant neoplasm originating from the surface ovarian epithelium. "The finding that KRT4 can be a potential biomarker of BPA exposure-associated ovarian cancer is of increasing importance given that this gene appears to be under the influence of estrogenic responses." (PMID 34062972, 2021). "When ER-positive ovarian cancer cells were treated with E2, KRT4 expression was dramatically down-regulated." (PMID 34062972, 2021). "Interestingly, when ZNF217 is silenced in ovarian cancer in vitro, the KRT4 gene was also significantly down-regulated." (PMID 34062972, 2021).
psoriasis (3 papers, 2016 to 2025). An autoimmune condition characterized by red, well-delineated plaques with silvery scales that are usually on the extensor surfaces and scalp. "Nevertheless, our data strongly indicate that cell-autonomous overexpression of il17rd in peridermal keratinocytes (krt4+) can induce psoriasis-like phenotypes by inhibiting cytoneme extensions, which subsequently leads to a reduction in Notch signaling in undifferentiated keratinocytes." (PMID 40767593, 2025). "Importantly, CRISPRa of the psoriasis-implicated enhancer in this keratinocyte cell line not only resulted in an increase in KLF4 expression, but a differential expression of 3 keratin genes (keratin 4, 13 and 15), confirming the importance of this enhancer and the KLF4 gene in skin cell function." (PMID 32366252, 2020).
dysplasia (2 papers, 2012 to 2021). A usually neoplastic transformation of the cell, associated with altered architectural tissue patterns. "Keratin 4 (CK4) is a marker of dysregulation of oral epithelial differentiation, CK10 expressed strongly in squamous cells, CK14 fell as the severity of the disease progressed from low- to high-grade dysplasia to SCC." (PMID 33889206, 2021). "Of the 65 surgical margins analyzed, 11 were keratin 4 negative independently of TNM: four with normal epithelium (4/33), two with hyperplasia (2/27) and five with dysplasia (5/5)." (PMID 23227181, 2012).
esophageal cancer (2 papers, 2024 to 2025). A primary or metastatic malignant neoplasm involving the esophagus. "According to another study, SIM2 upregulates CD24 and cytokeratin 4 (CK4), which are prognostic indicators for chemoradiotherapy and surgery in esophageal cancer." (PMID 38279998, 2024).
head and neck squamous cell carcinoma (2 papers, 2022 to 2024). A squamous cell carcinoma that arises from any of the following anatomic sites: lip and oral cavity, nasal cavity, paranasal sinuses, pharynx, larynx, and salivary glands. "KRT4 is identified as a hub gene of head and neck squamous cell carcinoma (HNSCC) using CytoHubba after conducting weighted gene co-expression network analysis and differential gene expression analysis between HNSCC and normal tissues." (PMID 38302910, 2024).
Hyperkeratosis (2 papers, 2018 to 2020). Hyperkeratosis is a histopathological term defining a thickened stratum corneum and may be present in many different skin conditions, with many possible overlaps. "When these genetic mutations occur in the genes encoding KRT4 or KRT13, this leads to cell fragility in the oral and/or ano-genital mucosa, which presents as white “spongy” plaques reflecting underlying cell fragility, cytolysis and compensatory overgrowth (hyperkeratosis)." (PMID 29476668, 2018). "Failure of this structural scaffold within KRT4- and KRT13-expressing keratinocytes leads to epithelial fragility and hyperkeratosis in the oral and anogenital mucosa." (PMID 29476668, 2018).
oral cancer (2 papers, 2012 to 2023). "Some of the DEGs common to OLP and oral cancer include KRT4 (down-regulated) and KRT16, KRT17, KRT10, and KRT75 (up-regulated)." (PMID 38234400, 2023). "In Western blotting, keratin 4 was negative (18/24) or showed low levels (3/24) in oral carcinomas and positive in most surgical margins (23/25)." (PMID 23227181, 2012).
cholesteatoma (1 paper, 2014). A pathologic process characterized by the proliferation of keratinizing squamous epithelium resulting in the accumulation of keratin and cells in the middle ear and/or mastoid. "The increased complexity of the cytokeratin pattern and the up-regulation of KRT4 suggest a lower grade of differentiation of cholesteatoma epithelium compared with the other keratinizing tissues." (PMID 25093596, 2014). "One keratin (KRT4) showed a higher level of expression compared with both the neck of cholesteatoma and EACS." (PMID 25093596, 2014). "This may lead to alterations in integrity and differentiation of the tissue (as suggested by the up-regulation of KRT4 in the cholesteatoma)." (PMID 25093596, 2014).
COVID-19 (1 paper, 2023). A disease caused by infection with severe acute respiratory syndrome coronavirus 2. "Six human PGs were identified as differentially expressed across the three subsets based on COVID-19 severity: Cytokeratin-4, ADP-ribosylation factor 4, Ig lambda chain V-I region HA, Protein S100-P, Sodium/glucose cotransporter 1, and Ig mu chain C region." (PMID 38188629, 2023).
dermatitis (1 paper, 2013). An inflammatory process affecting the skin. "Most notably, several RAR target genes involved in retinoid signaling were induced in allergen-induced dermatitis, whereas expression of RAR targets which are not implicated in retinoid signaling (Krt4, Rarres2, Tgm2) was not significantly altered." (PMID 23977003, 2013).
Glucose intolerance (1 paper, 2012). Glucose intolerance (GI) can be defined as dysglycemia that comprises both prediabetes and diabetes. "Tg(krt4:Hsa.myrAkt1)cy18 caused a rapid increase of body weight, hyperplastic growth of adipocytes, abnormal accumulation of fat tissues, and blood glucose intolerance at the adult stage." (PMID 22623957, 2012).
keratoconus (1 paper, 2023). A degenerative, structural disorder of the eye, characterized by a cone-shaped protrusion of the cornea. "Among all the listed keratins only KRT1, KRT4, KRT76, and KRT78 are upregulated in keratoconus all the other keratins are not differentially expressed." (PMID 37279397, 2023).
lipoma (1 paper, 2012). A benign, usually painless, well-circumscribed lipomatous tumor composed of adipose tissue. "The lipoma-like obese transformation in Tg(krt4:Hsa.myrAkt1)cy18 suggests that the normal physiology has been deregulated and is replaced with a metabolic syndrome-like phenotype." (PMID 22623957, 2012). "The lipoma transformation phenotype detected in Tg(krt4:Hsa.myrAkt1)cy18 is closely related to superficial subcutaneous lipoma (appearing in skin), chondroidlipoma (appearing in bone) and well-differentiated liposarcoma (appearing in muscle), which have been clinically reported in human patients." (PMID 22623957, 2012).
melanoma (1 paper, 2024). A malignant, usually aggressive tumor composed of atypical, neoplastic melanocytes. "As expected, we found enrichment of mitfa in melanoma cells and krt4 in keratinocytes, validating the successful cell-type isolation." (PMID 39229155, 2024). "To investigate the role of Twist in keratinocytes, we created new transgenic zebrafish in which the keratinocyte-specific krt4 promoter was used to drive the two zebrafish TWIST paralogs (twist1a and twist1b) in the presence of BRAFV600E-driven melanomas." (PMID 39229155, 2024).
Obesity (1 paper, 2012). Accumulation of substantial excess body fat. "Therefore, Tg(krt4:Hsa.myrAkt1)cy18 provides a unique and valuable lower vertebrate model to study the mechanism of obesity-induced metabolic deregulation for the first time." (PMID 22623957, 2012).
tumor (24 papers, 2009 to 2026). "It is also possible that luminal progenitor cells contribute to the intermediate population, as Krt4+ cells within the proximal and distal prostate have been described as tumor initiating cells after Pten loss." (PMID 36511483, 2022). "Some studies have also reported that HMOX1, SST, PLA2G2A, KRT4 and COL3A1 are associated with tumor progression and prognosis." (PMID 38461430, 2024). "Deregulation of KRT4 and KRT13 genes is associated with impaired epithelial differentiation and organization during tumor progression, and they are normally expressed in the oral cavity." (PMID 39140365, 2024). "The basal A subtype is enriched with basal markers such as cytokeratins (e.g., Cytokeratin 4), while basal-B exhibits a mesenchymal or a normal-like phenotype with overexpression of several genes related to tumor invasion and tumor stemness." (PMID 36768838, 2023). "Both TINCR and epithelial differentiation-associated genes, including IVL and KRT4, were significantly upregulated during OSCC cell calcium-induced differentiation but were reduced when cell dedifferentiation occurred in tumor spheres." (PMID 33732637, 2021). "Patients exhibiting keratin 4-negative margins showed higher rates of local recurrence, metastasis or a second primary tumor at the same anatomical site than patients with keratin 4-positive margins." (PMID 23227181, 2012). "Confirming what was observed in 1-DE and 2-DE, keratin 4 immunodetection experiments showed consistent differences in expression in tumor samples compared with the surgical margins." (PMID 23227181, 2012). "In 1-DE and 2-DE experiments, the absence or underexpression of keratin 4 in tumor samples was a consistent finding, confirming the results of several authors and validating the strategies used in the present study." (PMID 23227181, 2012). "These levels were lower in tumor than in normal samples for KRT4, KRT13, IL1RN, MAL and TGM3 (Wilcoxon test for paired data, p < 0.001)." (PMID 19835631, 2009). "Among down-regulated genes in tumor, KRT4 showed the highest order of magnitude (530-fold) and IL1RN the lowest (9-fold)." (PMID 19835631, 2009). "Moreover, among the human prostate luminal epithelial cell–type classifiers described previously, fNICD2-#1 luminal tumor foci expressed all 4 markers of luminal-C cells (TASCSTD2/PIGR/PSCA/KRT4)." (PMID 39024561, 2024). "There is evidence that Krt4 + cells may contribute to tumor initiation in the prostate." (PMID 36511483, 2022). "The suprabasal markers KRT4 and KRT13, commonly expressed in skin homoeostasis, were also differentially upregulated at RNA level in the tumours derived from the Ivl:BRAFV600E model." (PMID 41507151, 2026). "Quantification of GPx2 KD tumours and paired lung mets confirmed a higher percentage of carcinoma cells co-expressing p63 with KRT8/KRT14 than with KRT8 or KRT4 at both sites." (PMID 38238426, 2024). "The group I contain only two genes KRT4 and KRT13 which are under expressed in tumor data and over expressed in normal data." (PMID 39140365, 2024). "Only four SNVs in two genes, KRT4 and GOLGA6L10, were identified, resulting in the WTS and CNV data driving the biological narrative on this tumor." (PMID 24204627, 2013). "In conclusion, we showed the promising activity of TFDC-based immunotherapy in IDH-WT GBM and the association of low HLA-A expression and the absence of CCDC88A, KRT4, TACC2, and TONSL mutations in tumor cells of patients showing better prognosis." (PMID 37382632, 2023). "Low HLA-A expression and lack of CCDC88A, KRT4, TACC2, and TONSL mutations in tumor cells were correlated with better prognosis." (PMID 37382632, 2023). "Interestingly, all five dysplastic margins, which may represent a tumor precursor field or the presence of residual cancer cells, were keratin 4 negative; four of the patients developed tumor relapse or a distant metastasis." (PMID 23227181, 2012).
cancer (22 papers, 2006 to 2024). A tumor composed of atypical neoplastic, often pleomorphic cells that invade other tissues. "COL5A2, also known as collagen type V alpha 2 chain, has previously been reported to be involved in the pathology of cancer, and the protein encoded by KRT4 is a member of the keratin gene family and is related to differentiation." (PMID 31962291, 2020). "Interestingly, expression level of KRT4 protein was decreased in transition from normal esophageal epithelium to invasive tumor of stratified squamous epithelium and associated with cancer progression." (PMID 31090196, 2019). "In both control and cancer organoids, the expression of Hopx and the suprabasal keratinocyte markers Krt13, Krt4, and Krt6a increased with pseudotime while Lgr6-expressing cells were enriched in undifferentiated cells." (PMID 34785704, 2021). "Interestingly, the Krt4+ luminal cells had the highest number of copy number variations (CNVs), suggesting the presence of cancer-like characteristics of this cell cluster." (PMID 38781024, 2024). "Bioinformatics analysis of CLIP-seq data from ENCORI database further found that splicing factor DGCR8 could bind to KRT4 mRNA in cancer cells." (PMID 36811004, 2023). "The observed down-regulation of several extracellular matrix and basement membrane proteins, such as COL18A1 and NID2, could have great consequences on the integrity of the tissue and lead to altered differentiation (KRT4) and cancer-like alterations that may explain the characteristic phenotype." (PMID 25093596, 2014). "A similar phenomenon was observed with genes such as KRT4, LIPF, TG, and PGC, which are also almost exclusively expressed in specific tissues, making them less suitable for pan-cancer classification." (PMID 39118043, 2024). "Studies have widely reported that KRT4, IGFBP3, MMP10, MMP3, and TGFBI are involved in the pathogenesis of LC and other cancers." (PMID 38302910, 2024). "For example, both KRT4 and ATP12A are among the top 10 genes identified by both indicators as factors of promoting cancer onset." (PMID 38459043, 2024). "In contrast, careful examination of skin morphology at histological and cellular levels failed to reveal any sign of cancer transformation in Tg(krt4:Hsa.myrAkt1)cy18 skin." (PMID 22623957, 2012).
adenocarcinoma (1 paper, 2024). A common cancer characterized by the presence of malignant glandular cells. "The Krt4+ luminal cells shared marker genes that align with adenocarcinoma cells with luminal phenotypes." (PMID 38781024, 2024).
KRT4 also shares sentences with these, for which no sentence is quoted: infection (6 papers); chronic periodontitis (2); aspiration pneumonia (1); atopic dermatitis (1); brain cancer (1); breast (1); chordoma (1); chronic lung infections (1); clear cell renal cell carcinoma (1); colon cancer (1); colorectal cancer (1); cyst (1); cystic fibrosis (1); epidermolytic hyperkeratosis (1); Familial Woolly Hair Syndrome (1); gastric cancer (1); genetic disorder (1); hepatocellular carcinoma (1); hyperplasia (1); Hypotrichosis 13 (1); laryngeal carcinoma (1); leukemia (1); leukoplakia (1); liposarcoma (1); metabolic syndrome (1); myeloma (1); myocardial infarction (1); nasopharyngeal carcinoma (1); nonepidermolytic palmoplantar keratoderma (1); oral epithelial dysplasia (1).
A further 10 diseases each share a sentence with KRT4 in 1 paper.